CD4 (CD4 molecule)
Diseases named in the same sentence as CD4 in open-access papers (continued):
Sharing a sentence is not in itself a finding about the gene and the disease.
COVID-19 (continued). "Compared with the healthy control group, the counts of CD3+CD4+ and CD3+CD8+ T cells in COVID-19 patients decreased significantly." (PMID 37564653, 2023). "We also found higher frequencies of CD62L+ CD4+ and CD62L+ CD8+ Tregs in our severe COVID-19 patients." (PMID 36817450, 2023). "Regarding COVID-19 sequelae in IEI patients, a 16-year-old female with an idiopathic CD4+ lymphopenia (P3) is under otorhinolaryngology rehabilitation after 2 years’ persistence of taste and smell disturbances leading to a significant dietary restriction." (PMID 36742319, 2023). "To validate this assumption, we generated CD4+ and CD8+ TCR repertoires for 11 COVID-19 patients (“split” dataset) at multiple time points and applied our 47 SARS-CoV-2 TCRex models to this data." (PMID 37325653, 2023). "Future studies should investigate this finding in a larger patient population and determine the consistency of CD4+ T-cells, CD8+ T-cells, and ALC correlation and confirming T-cell exhaustion and apoptosis, especially during severe COVID-19 state." (PMID 37377785, 2023). "The mRNA COVID-19 vaccines, Pfizer BNT162b2 and Moderna mRNA-1273, induce Th1 and TFH cells and generate memory CD4 T cells that persist for at least six months post-vaccination." (PMID 37112761, 2023). "In COVID-19 convalescent patients, SARS-CoV-2 antigen-specific IFN-γ-secreting CD4+TRMs were detected." (PMID 36851616, 2023). "Another study also showed that coordination of SARS-CoV-2 antigen-specific immune responses, including antibody production and CD4 and CD8 T cell response, played a protective role in mild COVID-19 cases." (PMID 37117789, 2023). "In contrast, in the central memory (CM) CD4+ T cell subpopulation, a higher IFN-γ secretion (p = 0.0019) was detected in COVID-19 recovered children." (PMID 38005968, 2023). "In severe COVID-19, activated phenotype in CD8+ and CD4+ T cells have been found as compared to mild disease manifestation and noninfected normal controls." (PMID 37685949, 2023). "Recently it was reported that patients with severe COVID-19 exhibited higher levels of CD39+ T-cells, while the frequency of CD4 and CD8 T-cells expressing CD73 was decreased." (PMID 37818368, 2023). "In particular, the numbers of CD3+CD4+ and CD3+CD8+ T cells decreased to a greater extent in COVID-19 patients with myocardial injury." (PMID 37564653, 2023). "Various combinations of markers have been used for AIM assays in COVID-19; in agreement with others, the most of AIM+CD4+ T cells and the most of statistical correlations were herein found using CD69 and CD137." (PMID 37220145, 2023). "Surprisingly, we found cellular and metal ion homeostasis pathways enriched in the COVID-19-positive individuals compared to the healthy and recovered in the CD8+ T cell populations (CD8+ TCM and CD8+ TEM) as well as activated CD4+ T cells." (PMID 37886355, 2023). "In line with their different cellular origins, EV derived from healthy, vaccinated, mild, and severe COVID-19 convalescent donors all had distinct functional impacts on CD8 and CD4 T cells, suggesting different roles for EV in these settings." (PMID 37520724, 2023). "Of relevance, COVID-19 preexisting immunity is lower with HIV-infection, specifically with viral replication and poor CD4-cell count." (PMID 37090738, 2023). "Lymphocytic (CD4, CD8, CD20) infiltrates were scarce in both COVID-19 and influenza cases, whereas common myocarditis cases displayed—besides the prominent macrophage infiltrate—a marked mixed lymphocytic inflammatory infiltrate." (PMID 36371548, 2023). "Here we found that Australian First Nations peoples elicit effective immune responses to COVID-19 BNT162b2 vaccination, including neutralizing antibodies, receptor-binding domain (RBD) antibodies, SARS-CoV-2 spike-specific B cells, and CD4+ and CD8+ T cells." (PMID 37248417, 2023).
COVID-19 (continued). "In both comparison groups (healthy/positive and positive/recovered), we found that activated CD4+ T and CD8+ T cell populations (CD8+ TCM and CD8+ TEM) majorly expressed enriched pathways in the COVID-19 patients." (PMID 37886355, 2023). "The subgroup analysis of pregnant patients using immunophenotyping indicated that patients with moderate–severe forms of COVID-19 had a significantly reduced population of lymphocytes, CD4+ T cells, CD8+ T cells (only numeric), and CD4+/CD8+ index." (PMID 37046564, 2023). "SARS-CoV-2 spike-specific CD4+ and CD8+ T cells induced by prior infection or COVID-19 vaccination provide extensive immune coverage against the Omicron and Delta strains." (PMID 37110363, 2023). "Furthermore, our observations indicate that CD4+ T cells induced upon priming with the ancestral SARS-CoV-2 S1 and S2 epitopes largely retained the ability to recognize mutated antigens representing variants of the virus that emerged during the evolution of the COVID-19 pandemic." (PMID 37901229, 2023). "After the viral entrance, the absolute number of T-lymphocytes and the frequency of CD4+ and CD8+ T cells, and the CD4+/CD8+ ratio are decreased in COVID-19 patients." (PMID 37264452, 2023). "As poor CD4-count leads to lower cross-reactive antibodies (regardless of viral load), people living with HIV appear more vulnerable to COVID-19 and should be prioritized for vaccination." (PMID 37090738, 2023). "One of the first studies on the role of the adaptative immune system in COVID-19 showed reduced blood levels of both CD4+ and CD8+ T cells in COVID-19 patients (n = 522) compared to healthy subjects (n = 40)." (PMID 36941580, 2023). "A lower number of naïve cells and higher number memory cells was observed in both CD4+ and CD8+ T cells in COVID-19 patients than in healthy controls." (PMID 36732528, 2023). "The COVID-19 survivors reporting persistent symptoms following acute infection and determined to have PASC had increased CD4+ and CD8+ T cell activation for up to 180 days post SARS-CoV-2 infection." (PMID 38327763, 2023). "The MALAT1 anti-correlating gene signature shared by both CD4+ and CD8+ T-cells marked dividing T cells in both the lung and blood of COVID-19 patients." (PMID 36869729, 2023). "In comparison to normal/near normal areas within COVID-19-positive case 2, ROIs representing diffuse damage contained a markedly increased expression of CD3, CD4 and CD68, in terms of density per square millimetre." (PMID 36717223, 2023). "The CD patients exposed an increased expression of anti-inflammatory molecules like CD4, CD25 (IL-2Rα), and FOXP3, compared to severe COVID-19 patients and controls." (PMID 38138121, 2023). "In response to SARS-CoV-2 S-RBD and SARS-CoV-2 ICL, we observed significantly increased frequencies of CD4+ T cells expressing IFN-γ, IL-2, and IL-17A in MIS-C compared to children with COVID-19 and other infectious diseases." (PMID 38116577, 2023). "At baseline, there were significantly increased frequencies of CD4+ T cells expressing IFN-γ IL-2, TNF-α, and IL-17A in MIS-C compared with children with COVID-19 or with other infectious diseases." (PMID 38116577, 2023). "After receiving the AstraZeneca-Oxford COVID-19 vaccine, an increase in the production of tumor necrosis factor (TNF)-α and interferon (IFN)-γ by CD4+ T cells was observed." (PMID 37305120, 2023). "We confirmed the high expression of Rho GTPase activity in COVID-19 T cells (top), a trend that was consistent with both effector CD8+ T cells and effector memory CD4+ T cells (bottom)." (PMID 36992700, 2023). "Severe patients with COVID-19 not only had widespread cytokines rising, but also be accompanied with excessive decline of activation of T cells (CD3, CD4, CD8)." (PMID 38095633, 2023). "In the present study, a set of potential genes that reveal differential expression in B, CD4+ T, and CD8+ T cells induced by COVID-19 vaccination were identified." (PMID 36936955, 2023).
COVID-19 (continued). "We show evidence that a third dose of the licensed COVID-19 vaccines significantly boosted antibody and T-cell responses in PWH (VL undetectable and CD4 count >350 cells/μL)." (PMID 36196614, 2023). "Research on the immune response to inactivated COVID-19 vaccination among people living with HIV (PLWH) is limited, especially among those with low CD4+ T lymphocyte (CD4 cell) count." (PMID 36670363, 2023). "SARS-CoV-2 S reactive CD4+CD154+CD137+ T cells were induced in all HCs (N-term p = 0.016; C-term p = 0.008) and CVID R (N-term p = 0.004) after COVID-19 vaccination." (PMID 36932291, 2023). "The study found that, after the second dose of the COVID-19 vaccine, the mean levels of CD4+ T cells increased in the ABB C1® group, whereas there was a decrease of CD4+ T cells in the placebo group." (PMID 38235136, 2023). "To investigate the mechanisms associated with impaired T cell response in PLWH, we first compared the activation profile of CD4+ and CD8+ T cells between PLWH and HIV-uninfected COVID-19 convalescent individuals as well as healthy controls." (PMID 38343437, 2023). "This study aimed to examine the correlation between CD4+ and CD8+ cell counts and absolute lymphocyte count (ALC) in COVID-19 patients and analyze its difference based on the COVID-19 patients’ severity." (PMID 37377785, 2023). "Children with MIS had higher frequencies of CD4+ and CD8+ T cells expressing cytokines at baseline and upon SARS-CoV-2 antigen–specific stimulation in comparison to children with COVID-19 and/or other infections." (PMID 38116577, 2023). "In fact, in this step, there is a significant CD4+ T cell count drop, and CD8+ T cell and macrophages reduced function with cytokine cascade and subsequent COVID-19 exacerbation." (PMID 37185723, 2023). "It has been demonstrated that COVID-19 patients admitted to ICU were found to have significantly lower CD8+T and CD4+T counts, and these parameters were negatively correlated with survival." (PMID 37243203, 2023). "The present study aimed to investigate the temporal shifting in the T-cell population and their subsets, T-Helper (Th) cell (CD4) and T-Cytotoxic (Tc) cell (CD8) in COVID-19 patients." (PMID 37465793, 2023). "A significantly higher proportion of CD4+ and CD8+ T cells from COVID-19 patients expressed CD74 on the cell surface compared to healthy controls." (PMID 37946732, 2023). "Compared with healthy controls, the relative proportion of these cell types in COVID-19 patients showed an increase in myeloid cells, HSC, platelet and B cells, and a decrease in CD4+T, CD8+ T and NK cells." (PMID 36817436, 2023). "In this study, we investigated the dynamics of the neutralizing antibody levels and memory CD4+ and CD8+ T cell responses after the third COVID-19 mRNA vaccine dose in Finnish HCWs." (PMID 36756112, 2023). "In the patients who received BNT162b2 mRNA COVID-19 vaccination post-HCT, increases in NAb titers followed the surge of donor-derived SARS-CoV-2-specific CD4+ T cells." (PMID 36936918, 2023). "Although CD4+ and CD8+ significantly impact COVID-19 severity and mortality, these parameters are expensive and, in some places, inaccessible." (PMID 37377785, 2023). "The overall ratio of CD4+/CD8+ EVs in the mild (p = 0.0433) and severe COVID-19 patient groups (p = 0.0318) were lower than those in the HC group." (PMID 36982991, 2023). "To explore the nature of these associations, we profiled the transcriptomes of circulating immune cell subsets, namely CD4+ T cells, CD8+ T cells, monocytes, and NK cells, isolated during the first week after symptom onset (n = 14 patients with mild COVID-19)." (PMID 37225706, 2023). "Some included studies have reported that there is no significantly higher risk of developing severe COVID-19 among PLHIV compared to the general population or even advanced-stage HIV patients with lower CD4 counts that are severely immunocompromised may show less severe COVID‐19 symptoms." (PMID 36609313, 2023).
COVID-19 (continued). "CD69 expression showed increased upregulation in each T cell population (CD4+ and CD8+ effector and memory T, gdT, and MAIT) in acute COVID-19 patients compared to healthy controls, suggesting that T cells were activated under inflammatory conditions." (PMID 36732528, 2023). "Elevated expression of TGFB1 in CD4+ T cells and higher numbers of TGFB1-expressing T and CD14-positive cells have been observed in a small set of patients with severe COVID-19." (PMID 37255317, 2023). "Significantly greater frequencies of GrB and perforin expressing CD4 and CD8 T cells have been reported in severe COVID-19 cases than in the mild group during the later phase of illness." (PMID 36526890, 2022). "Here, we developed a machine learning procedure to find biomarkers that discriminate disease severity in individual immune cells (B cell, CD4+ cell, CD8+ cell, monocyte, and NK cell) using single-cell gene expression profiles of COVID-19." (PMID 35528178, 2022). "On the other hand, ADAM family members were upregulated in the T cells (Activated CD4+ T cells, CD4+ TCM, CD8+ TCM, CD8+ TEM) in active COVID-19 compared to the healthy and recovered." (PMID 36532041, 2022). "We find overall higher levels of CD4+ and CD8+ T cell activation, and more marked changes in cell markers, in COVID-19, suggesting a greater degree of CD8+ T cell exhaustion." (PMID 35216673, 2022). "Afterwards Petra Bacher (Christian-Abbrechts University Kiel) discussed low-avidity CD4+ T cell responses to SARS-CoV-2 in unexposed individuals and humans with severe COVID-19." (PMID 36225392, 2022). "In support of our findings, lymphocyte activation markers such as CD38, CD69, and CD44 are highly expressed on CD4+ and CD8+ T cells of COVID-19 patients, and CD73 absence in CD8+ T cells induces granzyme production in these individuals." (PMID 36248842, 2022). "Lymphocytopenia and modulation in lymphocyte balance associated with a decrease in levels of CD4+ cells, CD8+ cells, Th1, and Th2 cells and increased circulating CD4+ T cells, CD8+ T cells, Th2, PD-1, Tim-3, and LAG-3 in severe COVID-19." (PMID 36072602, 2022). "Hence TREM-2 may be involved in lung localised CD4+ T cells in COVID-19 patients." (PMID 36211412, 2022). "Diao and others reported a drastic reduction of CD4+ and CD8+ T cells, particularly in COVID-19 patients admitted to the ICU." (PMID 35647937, 2022). "Recently, studies also showed that the level of IL-6 in severe cases was markedly higher than that in mild and moderate cases, but the levels of CD4+ T cells, CD8+ T cells and NK cells were decreased, indicating immunosuppression in severe COVID-19 patients." (PMID 35270015, 2022). "Despite substantial reduction in CD4+ and CD8+T cell counts, the proportion of hyper-activated T cells was elevated in COVID-19 patients." (PMID 35284964, 2022). "We found activated CD4+ and CD8+ T cells were increased in frequency in all COVID-19 patient groups and remained elevated in convalescence." (PMID 35216673, 2022). "Despite the reduction of CD4+ and CD8+ T lymphocyte subsets in COVID-19-infected patients, our deconvolution analysis demonstrated that the Treg population was highly increased." (PMID 35922752, 2022). "Particularly in severe COVID-19 patients, higher frequencies of SARS-CoV-2-specific IFN-γ+CD69+CD4+ T cells, with a high expression of Cytotoxic T-Lymphocyte-associated Protein 4 (CTLA-4), were observed as compared to uninfected and convalescent patients." (PMID 36499533, 2022). "Relatively to mRNA vaccination, a robust induction of antigen-specific CD4+ and CD8+ T cells operated by COVID-19 vaccination has been demonstrated." (PMID 35720366, 2022). "Using high-content spectral flow cytometry and network-level analysis, we found that patients with severe COVID-19 had systemic hyper-activation of multiple cellular compartments, including CD8+ T cells, CD4+ T cells, and CD56+ natural killer cells." (PMID 35012610, 2022).
COVID-19 (continued). "Our search covered published studies reporting laboratory parameters for T-cell subsets (CD4/CD8) and IL-10 among confirmed COVID-19 patients." (PMID 35572964, 2022). "The frequencies of CD4+ and CD8+ T cells producing IFN-γ, TNF-α and IL-2 in response to SARS-CoV-2 Spike peptides were measured in randomly selected COVID-19 naïve healthy adults six months after the first vaccine dose." (PMID 36389704, 2022). "CD4+ and CD8+ T cell populations from COVID-19 patients in need of hospitalization also show increased expression of cell exhaustion markers, including the programmed cell death protein 1 (PD-1)." (PMID 35860236, 2022). "While the CD3+CD4+ and CD16+56+ lymphocyte counts are elevated in COVID-19 patients, TNF-α and IFN-γ decrease." (PMID 36423150, 2022). "In circulating T cells, both CD4+ and CD8+ T cells in the patient with myopericarditis after COVID-19 vaccine exhibited an activated phenotype defined by CD38+HLA-DR+ and PD-1+Ki-67+ compared to healthy and vaccine control groups." (PMID 35251049, 2022). "There have been several reports showing reduction in peripheral blood CD4+ and CD8+ T cells’ count in moderate and severe COVID-19 patients, which is quite similar to the earlier finding pertaining to SARS-CoV-1 infection." (PMID 35883618, 2022). "Our study clearly shows that activation of CD4+ and CD8+ T cells is a key finding in COVID-19 patients during active disease, and this is in agreement with others." (PMID 36003367, 2022). "Our results reflect this as the levels of CD4 and CD8 T cells and NK cells reduce with increasing severity, whilst pathway analysis contrasting severe COVID-19 to either moderate or mild COVID-19 also revealed downregulation of many T cell-related pathways." (PMID 35844004, 2022). "Deep and cell-specific analysis evidence that the surface expression of CD73 is impaired in CD4+ T cells and CD8+ T cells in patients with COVID-19, corroborating previously published data." (PMID 36248842, 2022). "Our results suggest the very high efficacy of mRNA COVID-19 vaccines in HIV-infected people on HAART and with a well-controlled disease (undetectable viremia and CD4+ count >500/mm3)." (PMID 36286201, 2022). "Both CD4+ and CD8+ T-lymphocytes are characterized by high expression of genes involved in the inflammatory process in severe COVID-19 patients." (PMID 35955721, 2022). "Dan and colleagues followed antigen-specific antibodies, memory B cells, CD4+ T cells, and CD8+ T cells up to 8 months after recovery from COVID-19, but a more recent study has shown sustained T and B cell responses over a year after infection." (PMID 36129963, 2022). "Supporting this, S-specific CD4 T cell TCR breadth and depth correlate with nAb titers in COVID-19 convalescent individuals." (PMID 35133988, 2022). "This information illustrates why trying to clarify the contribution of immune cells and mediators such as CD4+ T cells, CD8+ T cells, IL-2, IFN-gamma, and PD-1 to COVID-19 progression is extremely hard in polytreated patients already hospitalized." (PMID 35860236, 2022). "Compared to HDs, we found higher levels of Bak and Bax transcripts, in CD4 and CD8 T cells from COVID-19 individuals, respectively." (PMID 35066575, 2022). "Recent studies have shown that COVID-19 patients, compared to healthy controls, had significantly lower absolute numbers of total lymphocytes and subsets of CD3+, CD4+, and CD8+ T cells, CD19+ B cells, and CD56+ NK cells." (PMID 35711451, 2022). "To address this knowledge gap, we analyzed SARS-CoV-2–specific CD4+ and CD8+ T cells among pediatric participants with MIS-C, COVID-19 (1–2 months after symptom onset), and healthy children (HC)." (PMID 35044955, 2022). "A higher expression of chemokines (CXCL1, CXCL2, CXCL3, CXCL8 and CXCL16) were also found in the CD4+ TCM and Classical Monocytes in the COVID-19 patients." (PMID 36532041, 2022).